BRCA1 (BRCA1 DNA repair associated)
Diseases named in the same sentence as BRCA1 in open-access papers (continued):
Sharing a sentence is not in itself a finding about the gene and the disease.
breast cancer (continued). "Importantly, two key preclinical studies recently demonstrated that inhibition of RANKL significantly suppressed Brca1-mammary carcinogenesis suggesting that this may be a novel target for prevention in women at a high risk of developing breast cancer due to an inherited BRCA1 mutation." (PMID 31069010, 2019). "Activation of Akt has been shown to abolish the G2 cell cycle checkpoint by delaying nuclear translocation of BRCA1 during DNA DSB repair in a breast cancer cell line." (PMID 30521029, 2019). "The BRCT domain in BRCA1 gene of 40 Iranian patients with a family history of breast cancer was analyzed." (PMID 30806067, 2019). "BRCA1 and BRCA2 genes are the most commonly mutated genes that are associated with high breast cancer risk." (PMID 30975222, 2019). "More than 1,800 distinct BRCA1 and 2,000 BRCA2 mutations have been reported in the Breast Cancer Information Core (BIC) database." (PMID 31131559, 2019). "There is now compelling evidence that MRI is the most appropriate screening test for breast cancer in BRCA1/2 carriers." (PMID 30693378, 2019). "The high CTSS-expressing mammary tumors (1, 5, 6, and 7) showed low BRCA1 expression, whereas the low CTSS-expressing mammary tumors (2, 3, 4, and 8) showed high BRCA1 expression." (PMID 30006610, 2019). "High frequencies of mutations in BRCA1 and BRCA2 have already been observed in breast cancer patients of African ancestry from Nigeria and from the Bahamas." (PMID 30834239, 2019). "BRCA1 and BRCA2 gene mutations, confirmed to be linked to breast cancer in families, confer a 3.8- and 8.6-fold increased risk of developing prostate cancer, respectively." (PMID 31477094, 2019). "The other most common gene involved in breast cancer including TNBC is BRCA1/2; more than half of the hereditary TNBC cases (80%) carry mutation in BRCA1, while germ-line mutation in BRCA1 occurs in 15% of TNBC cases." (PMID 30871273, 2019). "For example, we now know that mutations in the tumor suppressor gene BRCA1 cause inappropriate exon skipping and inactivation of BRCA1, whereas upregulation of NUMA1 splice isoforms in breast cancer cause increased cell proliferation." (PMID 31329578, 2019). "Women with an inherited mutation in BRCA1 or BRCA2 experience similar frequency, severity, and timing of hematologic toxicities during curative intent breast cancer chemotherapy as matched wild‐type patients." (PMID 31407530, 2019). "Approximately 80% of breast cancers which develop in BRCA1-mutant carriers will have TNBC and the molecular mechanism facilitating tumor development is unclear." (PMID 33860286, 2019). "Loss of RANK signaling in breast cancer models drastically limits MPA‐induced and Brca1‐mediated tumorigenesis." (PMID 31267556, 2019). "BRCA1- and BRCA2-deficient breast cancers were further shown to have higher number of mutations and correspondingly and higher number of predicted neoantigens." (PMID 31022191, 2019). "In line with this proof of concept, we found that in patients with a low expression level of either BRCA1 or CCND1, the T cell activation score is negatively associated with the risk of mortality in breast cancer." (PMID 31023256, 2019). "In this age group there is a higher proportion of patients with pathogenic variants in genes that predispose to breast cancer, such as BRCA1 or BRCA2, compared with patients who have onset of breast cancer at an older age." (PMID 31491032, 2019). "It is well-known that poly ADP-ribose polymerases (PARPs) form SL interactions with the two breast cancer genes BRCA1 and BRCA2." (PMID 31870274, 2019). "Investigating BRCA1 and BRCA2 mutation status in ovarian and breast cancer tissues patients, has a key role in addressing the therapeutic choices." (PMID 31065452, 2019).
breast cancer (continued). "To elucidate the physiological role of CTSS in mammary tumorigenesis, we examined the relationship between CTSS and BRCA1 expression in spontaneously induced rat mammary tumors." (PMID 30006610, 2019). "In a phase I dose escalation study (NCT00749502), four of 12 breast cancer patients were BRCA1/2-mutant carriers." (PMID 30934991, 2019). "A minority of breast cancer patients offered germline BRCA1/2 testing would likely benefit from pre-test counseling—telephone or in-person—as a complement to written information." (PMID 30311024, 2019). "This study also confirmed the utility of NGS for performing the genetic testing of hereditary breast cancer based on BRCA1 and BRCA2 genetic alterations." (PMID 31131559, 2019). "Interestingly, a positive association with the risk of breast cancer was observed for the high levels of vitamin B12 in women who abused alcohol and for the high folate levels in women overall as well as in women with BRCA1/2 mutations and in women with estrogen receptor beta negative tumors." (PMID 31540424, 2019). "It has been recently estimated that the cumulative risks of breast cancer to age 80 years was 72% for BRCA1 and 69% for BRCA2 carriers." (PMID 31741787, 2019). "The MDA-MB-231 cell line is wild type for BRCA1 and PIK3CA, two genes often mutated in breast cancer, whereas the SUM159PT cell line contains wild type BRCA1 but also an activating PIK3CA mutation." (PMID 31362447, 2019). "As a consequence, germline BRCA1/2 testing can now be offered to a much larger number of breast cancer patients than what previously was possible." (PMID 30311024, 2019). "Reconstitution of BRCA1 resulted in significant decrease of the CSC-like populations in breast cancer cells whereas down-regulation of BRCA1 resulted in significant increase of the CSC-like populations." (PMID 31273285, 2019). "In our result, the average age at breast cancer onset between the BRCA1 group and BRCA2 group was nearly equal." (PMID 31143373, 2019). "Obviously, we can see that NF1, BRCA1, FOXO1, PTEN, CAV1 and WT1 are linked with breast cancer genes in PPI network or pathway network." (PMID 31760937, 2019). "One of them was found in early AAO cohort whereas another double heterozygote BRCA1/2 female had a late breast cancer manifestation." (PMID 31395037, 2019). "This generates a BRCA1 deficient-like phenotype in breast cancer, whereupon AKT1 is necessary for the BRCA1-associated breast cancer cell proliferation." (PMID 31752925, 2019). "Collectively, these demonstrated that BRCA1- and BRCA2-deficient breast cancers have different immunophenotype notwithstanding the similar genomic features shared between these groups." (PMID 31022191, 2019). "BRCA1 and BRCA2 have been described as “breast cancer susceptibility genes,” so failure to properly repair mutations in these genes increases the risk for breast cancer." (PMID 31715586, 2019). "The BRCA1 or BRCA2 mutation detection rate in female breast cancer patients depends on factors such as age at diagnosis and breast cancer subtype." (PMID 31760547, 2019). "This is indicated by the negative correlation between total protein content and the content of AGE (r = −0.83, p < 0.00001), MDA (r = −0.41, p = 0.0454), and TAS (r = −0.67, p = 0.0013) in the unstimulated saliva of BRCA1+ patients with breast cancer." (PMID 31597313, 2019).
breast cancer (continued). "While most hereditary cases of breast cancer are associated with pathogenic variants in BRCA1 and BRCA2, less common variants in other genes have also been associated with increased risk of developing breast cancer." (PMID 30759220, 2019). "TNBC is a subtype of breast cancer with the poorest clinical outcome that shows strong similarities to BRCA1mut or BRCA1-dysfunctional breast cancers." (PMID 31014367, 2019). "Individuals with hereditary breast and ovarian cancer syndrome (HBOC), which is caused by germline pathogenic variants of BRCA1 or BRCA2, have an increased risk for breast cancer, ovarian cancer, prostate cancer, and pancreatic cancer." (PMID 31143373, 2019). "Germline pathogenic variants in DNA repair genes BRCA1, BRCA2, PALB2, ATM, and CHEK2 are associated with breast cancer risk." (PMID 31700994, 2019). "Hereditary and genetic factors, such as a personal or family history of breast cancer and some inherited mutations, BRCA1 and BRCA2, are important predictors of the development of breast cancer." (PMID 31578436, 2019). "Specifically, it binds to the BRCA1 C Terminus (BRCT) domain of the tumor suppressor BRCA1 and inhibits BRCA1 in breast cancer." (PMID 31405076, 2019). "It has been found that in MCF-7 and MDA-MB human breast cancer cells, n-3 PUFAs can effectively promote the expression of breast cancer suppressor genes BRCA1 and BRCA2." (PMID 31182104, 2019). "Peripheral blood DNA methylation at the known breast cancer susceptibility genes BRCA1 and ATM has been found to be associated with elevated breast cancer risk." (PMID 31636290, 2019). "Given that EMT transcription studies in breast cancer mainly focus on triple negative breast cancer (BC) subtype BRCA1 addicted, more information is needed in luminal cancers." (PMID 31110518, 2019). "It is worth mentioning that any alteration in the expression of genes that regulate or interact with BRCA1 can negatively affect to the function of this protein and promote the development of breast cancer." (PMID 31225502, 2019). "One hundred four families with a history of breast cancer were sampled in different regions of Colombia, and the BRCA1 gene and exon 11 of the BRCA2 gene were sequenced." (PMID 31341521, 2019). "BRCA1, a well-known breast cancer tumor suppressor, was altered in 4 WHO°I IVMs and in one WHO°II and its recurrent tumor (n = 6/18)." (PMID 31470906, 2019). "The BRCA1 c.224_227delAAAG found in our study was previously identified in in 2 out of 53 patients with breast cancer of Kurdish Jewish descent." (PMID 31488070, 2019). "Deleting the Brca1 gene in mouse luminal lineage cells generates tumors that are similar to human BRCA1 breast cancer and sporadic basal-like breast cancers according to histological and transcriptional profiling analyses." (PMID 31013830, 2019). "Inherited mutations in BRCA1 and BRCA2 are associated with increased risk to breast cancer and are enriched in patients with an early age of diagnosis and family history of breast and ovarian cancer." (PMID 31022191, 2019). "The top pathways included the hereditary breast cancer and role of BRCA1 in DNA damage response signaling pathways." (PMID 30909550, 2019). "This study utilizing only the direct sequencing methodology of BRCA1 gene and exon 11 of BRCA2 gene aimed to identify mutations that increase the familial susceptibility to breast cancer in families from different regions of Colombia." (PMID 31341521, 2019). "Taken together, our results suggest that PALB2-associated breast cancers with bi-allelic inactivation are similar to breast cancers with BRCA1 and BRCA2− bi-allelic inactivation in terms of genetic instability and genomic features indicative of HRD." (PMID 31428676, 2019).
breast cancer (continued). "Over-expression of phosphoglycoprotein (P-gp) has been previously suggested as a mechanism of resistance to the PARP inhibitor olaparib in mouse models of Brca1/2-mutant breast cancer." (PMID 31080552, 2019). "To verify this, we first confirmed that BRCA1 indeed physically interacted with ZBRK1 in mouse MEF‐BRCA1+/+ cells and human breast cancer cell lines MCF‐7." (PMID 30714292, 2019). "Among the 21 patients with breast carcinoma histories in first-degree relatives, 4 (19%) patients had BRCA1/2 positivity." (PMID 30713775, 2019). "An additional BRCA1 3′UTR SNP, rs3092995, induces an elevated breast cancer risk in African American women, with the G allele predominant in BC patients, as compared to control subjects." (PMID 30897768, 2019). "In our study, the BRCA1/2 positivity was 19% in the breast carcinoma patients with first-degree relatives having breast carcinoma histories." (PMID 30713775, 2019). "Among the 7 patients with bilateral breast carcinomas, only 1 (14%) patient exhibited BRCA1/2 positivity." (PMID 30713775, 2019). "One carcinoma center found a BRCA1/2 mutation prevalence of 23% (BRCA1 = 17% and BRCA2 = 6%) in breast carcinoma patients under 35 years old." (PMID 30713775, 2019). "We genotyped blood-derived DNA samples from 1820 unselected breast cancer (BC) cases and 1968 controls, using the BRCA1 c.4096+3A>G SNP Taqman assay." (PMID 31683985, 2019). "Breast carcinoma cells submitted to hypoxia (0.01% O2) showed a decrease in H3K4 methylation (H3K4me2,3), associated with increased transcriptional activity in BRCA1 and RAD51 promoter regions, and, therefore, presented a decreased expression of these genes." (PMID 30939818, 2019). "In one study of Korean women with breast carcinoma histories in their families, the BRCA mutation prevalence was 21.7% (BRCA1 = 9.3% and BRCA2 = 12.4%)." (PMID 30713775, 2019). "In our study, we found a BRCA1/2 mutation prevalence of 19.5% (BRCA1 = 9.75% and BRCA2 = 9.75%) in breast carcinoma patients under the age of 40 years old." (PMID 30713775, 2019). "Among the 8 patients with left breast carcinomas, the BRCA1 and BRCA2 were positive in 3 patients (27.2%) and 5 patients (62.5%), respectively." (PMID 30713775, 2019). "The presence of germline and somatic deleterious mutations in the BRCA1 and BRCA2 genes has important clinical consequences for breast cancer (BC) patients." (PMID 31454914, 2019). "Nevertheless, the response of the PC-3 cells to PARP inhibition is comparable to previous studies in BRCA1/2-defective breast carcinoma cells." (PMID 31102368, 2019). "The guidelines recommend considering the BRCA1 and BRCA2 germline mutations in female patients with breast carcinomas." (PMID 30713775, 2019). "Exposure to radiation upregulated KPNA2 expression in human colorectal cancer HT29 and HCT116 cells and breast carcinoma MDA-MB-231 cells together with the increased expression of DNA repair protein BRCA1." (PMID 31212646, 2019). "At the end of follow-up, 15 mutation carriers (12 BRCA1 and 3 BRCA2) exposed to ovarian stimulation for IVF had developed breast cancer." (PMID 29937543, 2018). "In a prospective, single-arm study, comprehensive BRCA1/2 testing was offered to unselected patients with newly diagnosed breast cancer at three hospitals in south Sweden (BRCAsearch, ClinicalTrials.gov Identifier: NCT02557776)." (PMID 29164420, 2018). "A part of the DNA sequence of the BRCA1 breast cancer gene (target) was chosen as the target in this work, because it has been reported that the replacement of guanine (G) with thymine (T) in this gene (mutant) is linked to familial breast and ovarian cancers." (PMID 30404141, 2018). "Mutations in two prominent susceptibility genes, BRCA1 and BRCA2, were identified as major risk factors for breast cancer." (PMID 30249004, 2018). "The distribution of onset age for breast cancer and ovarian cancer was compared among BRCA1/2-positive and BRCA1/2-negative groups." (PMID 29176636, 2018).
breast cancer (continued). "The aim of this study was to retrospectively evaluate platinum-based neoadjuvant chemotherapy for BRCA1-positive breast cancers." (PMID 29719582, 2018). "BRCA1 and BRCA2 are the two most commonly mutated high-penetrance genes and about 15–20% of the familial breast cancer risk is attributable to germline mutations in one of these two genes." (PMID 30116257, 2018). "Larger randomized studies and longer follow-up times are necessary to evaluate the role of platinum-based therapies in BRCA1-positive breast cancer." (PMID 29719582, 2018). "The roles of BRCA1 in the oncogenesis of breast cancer have been widely reported and researches even suggest that patients with BRCA1 mutations have a possibility of 50%–80% to develop breast cancer before the age of 70." (PMID 29485617, 2018). "The risk for women with BRCA1- and BRCA2-positive breast cancer of developing primary ovarian cancer is 15–65%." (PMID 29177593, 2018). "On a sample of 266 breast cancer (BC) and 101 breast/ovarian cancer families (BOC) Sanger sequenced for BRCA1/2 genes, 97 (26%) carried deleterious mutations." (PMID 29271107, 2018). "In Brca1 mutant mice, the loss of RANKL reduced mammary tumors and tumor progression, and the inhibition of RANKL prevented mammary tumor development." (PMID 30572612, 2018). "Those genes are the epidermal growth factor receptor (EGFR) and the breast cancer genes BRCA1 and BRCA2." (PMID 30546831, 2018). "In one study, mutations in ten different genes associated with breast cancer were evaluated in CMT (by iPLEX genotyping of sixty-three single nucleotide polymorphisms), but only BRCA1 and BRCA2 were significantly associated with the development of this tumor." (PMID 30373614, 2018). "For example, in the breast cancer group of genes, the BRCA1 oncogene is normally expressed in proliferating cells." (PMID 30042356, 2018). "When detected outside of the dedicated follow-up programs, the prognosis is bad for breast cancer in both BRCA1 and BRCA2 carriers." (PMID 28939999, 2018). "In carriers of breast cancer susceptibility genes 1 and 2 (BRCA1/BRCA2) mutations, pregnancy also increases the risk of breast cancer." (PMID 30202672, 2018). "This is consistent with a previous report that demonstrated that TGFβ signaling in wild‐type BRCA1/2 breast cancers down‐regulates HR gene expression, and renders breast cancer cells more sensitive to PARPi." (PMID 30467127, 2018). "The results of the study confirm the high pCR rate of BRCA1-positive breast cancer after platinum-based neoadjuvant chemotherapy." (PMID 29719582, 2018). "As aberrant BRCA1 promoter methylation is found in approximately 10% of sporadic breast cancers, we first measured the levels of epigenetic silencing of BRCA1 and analyzed BRCA1 expression and nuclear foci formation in PDX samples." (PMID 30377213, 2018). "The relevant variant was detected in four of seven family members, two of whom had been diagnosed with a typically associated tumor (breast cancer in PALB2 and BRCA1 variants)." (PMID 29909963, 2018). "Models should not be too generic, as they should include important read-outs of cancer types such as AR for prostate or ER and BRCA1 for breast cancer allowing them to better separate cancer subgroups." (PMID 30733688, 2018). "We show that BRCA1 influences expression of miR-29b-1-5p in human breast cancer cell lines, possibly via promoter binding and influencing transcriptional regulation." (PMID 30323900, 2018). "One of these, the hereditary breast and ovary cancer syndrome (HBOCS), associated with germline mutations in BRCA1 and BRCA2 genes, is believed to cause approximately 10–15% of all breast cancers (BCs)." (PMID 29456621, 2018). "Treatment of Brca1-mutant mammary tumors with vinblastine, which alters cyclin B1 level, significantly reduced tumor progression with reduction of survival and induction of apoptosis." (PMID 30327455, 2018).